TNF (tumor necrosis factor)
Diseases named in the same sentence as TNF in open-access papers (continued):
Sharing a sentence is not in itself a finding about the gene and the disease.
colitis (continued). "Besides, TNF-α/NF-κB/JMJD2D has a protective effect against DSS- or AOM/DSS-induced colitis via activation of Hh/Gli1/Gli2." (PMID 34702800, 2021). "Moreover, sodium butyrate was reported to ameliorate colitis in mice with decreased levels of TNF-α and IL-6." (PMID 33748287, 2021). "To begin to understand what difference might be leading to differences in regulation of IL-33 in the two models of murine colitis, we examined tissue RNA expression for two cytokines that have previously been shown to induce IL-33, TNF and IL1-β16." (PMID 33953267, 2021). "Upon induction of colitis, significant increases in TNF-α, IL-1β, and IL-6 production were observed in mouse colons, and CME treatment could dose-dependently reduce the production of these cytokines." (PMID 34616300, 2021). "In both experiments, the initial inflammatory response to induced colitis (1 day post induction) included elevated gene expression of proinflammatory cytokines TNFα, as well as clinical markers of disease such as hematochezia and weight loss, apathy and dull coat." (PMID 33897648, 2021). "The WT mice that were reconstituted with Drd5−/− bone marrow were more prone to DSS-induced colitis with greater body weight loss, a higher DAI score, shorter colons, and more infiltrating inflammatory cells as well as higher levels of TNFα, IL-6, and CCL2 in serum." (PMID 34884737, 2021). "Since ILK mediates activation of the TLR4/NF-κB/TNF-α signaling pathway by LPS (a TLR4 agonist) in colitis, it is possible that ILK could have an impact on regulating the activities of different TLRs in cancer." (PMID 34163519, 2021). "To evaluate colitis severity, we measured the expression of different pro-inflammatory cytokines and chemokines and found that the same supplement suppressed the pro-inflammatory cytokines IL-6 and TNFα and the chemokines Cxcl1 and Ccl3." (PMID 34071180, 2021). "Previous studies have shown that NAM prompts TNF-α production and reduces IL-10 levels in colitis." (PMID 33748287, 2021). "In mice fed on PD, RS exposure for 14 days markedly worsened colitis symptoms afterward, as shown by colonic shortening, histology, loss of goblet cells, and inflammatory cytokines (IL-6, MCP-1, TNF-α)." (PMID 33431867, 2021). "In this study, consistent with IBD patients, high levels of pro-inflammatory factors (IL-6, IL-1β and TNF-α) were found in mice with DSS-induced colitis, while these pro-inflammatory factors were reduced after treatment with GPH extracts, and high-dose extracts had a stronger inhibitory effect." (PMID 34829046, 2021). "Our recent in vitro and in vivo studies observed that active vitamin D prevented the host from the detrimental effects of overwhelming inflammation by downregulating pro-inflammatory responses (IL-6, TNF-α, IL-8, and IL-1β) in Salmonella-infected IECs and decreased the severity of colitis in mice." (PMID 34943999, 2021). "Moreover, prophylactic EGCG tended to reduce the plasma levels of IL-1β, IL-6, IL-8, and TNF-α in mice with colitis." (PMID 34493333, 2021). "Furthermore, the expression of proinflammatory cytokines, including TNFα and IL-6, significantly increased in mice with colitis, whereas the DSS + SP@Curcumin–treated group showed the similar expression to that of nontreated mice." (PMID 34818040, 2021). "Furthermore, orally gavaged or intraperitoneally injected buspirone alleviated colitis: it reduced myeloperoxidase activity, TNF-α and IL-6 expression, and NF-κB+/CD11c+ cell population." (PMID 33731795, 2021). "Likewise, it has been suggested that the systemic production of TNF-α protects against the spontaneous development of colitis and CAC." (PMID 34681866, 2021). "Additionally, all groups differed significantly in serum GSH and serum TNF-α compared to the untreated acetic acid-induced colitis group." (PMID 33441125, 2021).
colitis (continued). "Nuclear factor (NF)-κB activation was markedly elevated and resulted in higher expression levels of downstream effectors (C–C motif chemokine ligand 20, interleukin [IL]-1β, IL-6, and tumor necrosis factor [TNF]-α) in colonic epithelial cells isolated from PBLDIEC−/− mice than WT mice with colitis." (PMID 34059646, 2021). "JUG reversed the DSS-induced up-regulation of proinflammatory cytokines, including interleukin (IL)-6, 12, 21, and 23, and tumor necrosis factor-alpha, and anti-inflammatory cytokines, such as IL-10 and transforming growth factor-beta, in the serum of the colitis mice." (PMID 34421890, 2021). "IAP ameliorated colitis in mice and inhibited LPS-induced IL-6 and TNF-α production." (PMID 34944428, 2021). "In our study, we found that Xi Lei San could significantly inhibit NLRP3 inflammasome activity in rats with DSS-induced colitis and also in TNF-α-induced CACO2 cells." (PMID 33967625, 2021). "Exercise significantly decreased TNBS-colitis macroscopic and microscopic severity, increased colonic blood flow, and attenuated plasma TNFα, IL-6, MCP-1, IL-1β and leptin levels in mice fed either a HFD (70% EAF) or a standard regular chow diet compared to their sedentary counterparts." (PMID 33603741, 2020). "Il10-/- mice that are also TNF-deficient (Tnf-/-Il10-/-; termed “T/I” mice) uniformly develop moderate to severe colitis by age 4–6 weeks without the need for exogenous triggering." (PMID 32941525, 2020). "Moreover, MOPE treatment significantly inhibited the protein expression of TNF-α in colon tissue after DSS-induced colitis." (PMID 33299453, 2020). "Interestingly, prophylactic blockade of TNF strikingly ameliorates the treatment-induced worsening of the colitis." (PMID 31974523, 2020). "TNF expression in TTP–/–TH17 cells may also contribute to the DSS-induced colitis in the CD4CreTTPf/f mice." (PMID 32922402, 2020). "According to the results, plasma and rectum TNF-α levels increased significantly in the colitis and saline treatment group, compared with the control group (P < 0.0001 and < 0.001, respectively), while the adenosine treatment decreased these levels nearly down to the control levels (P = 0.018)." (PMID 32074166, 2020). "Alistipes can effectively inhibit inflammation via preventing LPS-induced TNF-α release at higher concentrations and has been found at lower levels in the gut of patients with hepatocellular carcinoma, colitis and non-alcoholic fatty liver disease." (PMID 32273874, 2020). "In addition, IFX treatment by AC-IFX-L and EAC-IFX-L-based nanocomposites not only showed a significant anti-inflammatory effect, but also remarkably decreased TNF-α level in a DSS-induced mouse colitis model." (PMID 32933548, 2020). "Furthermore, studies with mice models of colitis have showed that exogenously added GABA attenuated the colitis-induced TNF-α increase and instead increased the production of the anti-inflammatory cytokine IL-10." (PMID 33066564, 2020). "As an irritant agent, AA induces the colitis involving infiltration of colonic mucosa with neutrophils and increased production of inflammatory mediators, such as hydrogen peroxide, nitric oxide (NO), myeloperoxidase, and TNF-α." (PMID 32074166, 2020). "Thus, indirubin ameliorates DSS-induced colitis by suppressing the expression of colonic TNFα, IFNγ, and IL-2 and upregulating IL-10." (PMID 32855621, 2020). "Some reports suggest that murine colitis worsened after anti-TNF blockade." (PMID 33519819, 2020). "In addition, IFN-γ activates M1 macrophages, which then produce TNF-α and reactive oxygen species (ROS) and respond to the pathogenesis of colitis." (PMID 32485960, 2020). "Of note, also in our previous study applying human microbiota associated IL-10-/- mice without pre-existing colitis, C. coli induced systemic TNF-α secretion, whereas splenic and blood samples were all culture-negative for C. coli." (PMID 32664563, 2020).
colitis (continued). "Furthermore, the expression of pro-inflammatory cytokines, like IL-6, TNF-α and IL-1β, was decreased in a peptidoglycan-polysaccharide-induced colitis rat model." (PMID 32722619, 2020). "Colitis increased secretion of IFNγ and of IL-6 and tended to increase the secretion of TNFα." (PMID 32156075, 2020). "We investigated whether oral CG-598 treatment could ameliorate colitis comparable to an anti-TNF blocker by evaluation of body weight changes, disease activity index, and shortened colon lengths." (PMID 33519819, 2020). "The use of PD-L1 blocking mAb in this model prevented the development of experimental colitis in association with the decreased expansion of pathogenic T cells and downregulated inflammatory cytokine production (i.e., IFN-γ, TNF-α) by lamina propria CD4+ T cells." (PMID 33271941, 2020). "Also, the loss of function in UHRF1 reduces the methylation of the TNF-α promoter in macrophages, indicating the regulatory role of UHRF1 in the mouse model of colitis." (PMID 32848509, 2020). "In the mouse T cell-transfer model of colitis used in the present study, the inflammation was characterized by accumulation of Th1 and T17 cells in colonic lamina propria and mesenteric lymph nodes with overexpression of INFγ and TNFα." (PMID 32448932, 2020). "Moreover, nanoparticles derived from grapefruit are taken up by intestinal macrophages and improve experimental colitis in mice by upregulating the expression of heme oxygenase-1 (HO-1) and inhibiting the production of IL-1β and TNF-α." (PMID 32365813, 2020). "The level of pro-inflammatory cytokines (TNFα, IL-1β and IL-6) in the blood serum, as well as IL-1β in the colon tissue of mice with colitis receiving algae extract, was lower than that in control animals, and the level of anti-inflammatory interleukin IL-10 was higher." (PMID 32486405, 2020). "Furthermore, mRNA expression of genes encoding cytokines including IL-6, IL-1β, and TNF-α, and protein expression of COX-2 and iNOS were upregulated in the colon tissue of mice with DSS-induced colitis." (PMID 32059355, 2020). "Moreover, CA4P exacerbated the pathological features of colitis and significantly increased proinflammatory cytokines (IL-1β, IL-6, TNF-α) and inflammatory cells (neutrophil, lymphocyte, monocyte)." (PMID 32265711, 2020). "However, in a rat colitis model, the serum level of TNF-α was significantly lower in the RJ treatment group (p < 0.05) than in the control." (PMID 33050250, 2020). "Similarly, the anti-inflammatory effect of His through down-regulation of TNF-α mRNA expression was reported in mice with colitis." (PMID 32695286, 2020). "Notably, the plasma levels of IL-6, IL-1β, and TNFα from DSS colitis mice were significantly diminished in mice that received anti-Myl9/12 Ab treatment in comparison to those that received control Ab treatment." (PMID 33584659, 2020). "Oral treatments with the compounds significantly suppressed TNBS-induced expressions of IL-10, in addition to TNF-α, IL-6, and IL-1β in colon tissues, indicating that an anti-colitis activity of the compounds led to the resolution phase of TNBS-induced inflammation." (PMID 31619080, 2020). "In mice with dextran sulfate sodium (DSS) or 2,4,6-trinitrobenzenesulfonic acid-induced colitis, MaR1 reduced leukocyte infiltration, inhibited neutrophil migration, and reduced the levels of the following proinflammatory cytokines: IL-1β, TNF-α, IL-6, and INF-γ." (PMID 32751593, 2020). "Only pretreatment with LA at the high dose, together with sulfasalazine, significantly protected from the increase of the TNF-α concentration in comparison to the colitis group (p < 0.01), but the action of combined treatment was not greater than the administration of sulfasalazine alone (p = NS)." (PMID 33299531, 2020). "However, recurrence of ICI colitis was rare even in patients with preexisting autoimmune diseases that were treated with TNF-α inhibitors." (PMID 33271941, 2020).
colitis (continued). "Both in the DSS-induced colitis model and in the colitis model induced by adoptive transfer of naive T cells, BDNs prevented intestinal damage and determined a reduction in the expression of TNF-α, IL-17A, and IFN-γ and an increased expression of IL-10." (PMID 33336066, 2020). "Meanwhile, the characteristics of colitis coupled with many other chronic inflammatory diseases are characterized with the production of more pro-inflammatory cytokines such as IL-6, IL-1β, and TNF-α in serum and tissue." (PMID 32670051, 2020). "Moreover, MDEs were shown to downregulate the inflammatory process in part through the downregulation of key cytokines involved in colitis, such as IL-6 and TNF-α." (PMID 32858892, 2020). "Budesonide-entrapped krill oil-incorporated liposomes suppressed TNF-α in colitis models." (PMID 32486445, 2020). "DSS-induced colitis induced a significant increase of TNFα only in the cheese matrix group." (PMID 32156075, 2020). "Several authors have shown that, during the course of DSS-induced colitis, the onset of various symptoms is accompanied by an increase in oxidative stress, an increase in inflammatory markers (TNF-alpha, IL-1, NO, and NF-kB), and an increase in the expression of iNOS." (PMID 32565862, 2020). "Cytokines IL-1β, IL-6, and TNF-α can activate NF-κB phosphorylation in colitis." (PMID 33664740, 2020). "Indeed, in vivo NAC treatment successfully ameliorated acetic acid-induced colitis by reversing pro-inflammatory mediators TNF-α, IL-6, and MPO in rats." (PMID 33224136, 2020). "In TNBS-induced colitis, cytokine imbalance was demonstrated by high expression of proinflammatory cytokines (TNF-α, IFN-γ, IL-1β, and IL-17) and low expression of anti-inflammatory cytokines (IL-4 and IL-10) to induce inflammatory damage to the colonic mucosa." (PMID 30894816, 2019). "Taken together, despite its discovery as a tumour necrosis factor, elevated TNFα signalling might exert rather harmful functions during the development of CRC and colitis-associated CRC." (PMID 30995806, 2019). "The anti-inflammatory effects of KA were consistent with the effects on pro-inflammatory mediators, i.e., NO, PGE2, IL-6, and TNF-α, in LPS-induced macrophages; they are known to be involved in the regulation of immune reactions, inflammation, and, in some cases, colitis and death." (PMID 31569788, 2019). "Next, to confirm the anti-inflammatory effect of SIF on the increased DSS-induced colitis model, we investigated the mRNA expression levels of inflammatory cytokines such as TNF-α, IL-1β, IL-6, MCP1 and inflammatory enzymes iNOS and COX-2 in colon tissues assessed by quantitative RT-PCR." (PMID 31362418, 2019). "Indeed previous researches on experimental colitis have shown a positive correlation of TNF-α, IL-1β, and IL-6 levels in animal with colitis and the degree of colonic inflammation." (PMID 32641944, 2019). "Also, ASA-iGMSCs induced more significant reductions in serum TNF-α and IL-17 level in colitis mice compared with the iGMSC group." (PMID 31796122, 2019). "Animals studies show that a daily oral administration of BJ extract (20 mg/kg) in mice subjected to experimental colitis reduced colon levels of TNF‐α, IL‐1ß (p < 0.01), NK‐kb p65 (p < 0.01), p‐JNK (p < 0.01), and the degree of positive staining for nitrotyrosine." (PMID 30847114, 2019). "In agreement with this study, it was reported that Lactobacillus reuteri and L. fermentum could depress the expression of pro-inflammatory factor TNF-α in a rat colitis model." (PMID 31291967, 2019). "In contrast, but in agreement with increased UC disease severity observed in FliiTg/Tg mice, distal colons of these colitis-induced mice showed an exacerbated immune response with significantly increased expression of Th1 and Th2 cytokines including TNF-α, IFN-γ, IL-5 and IL-13." (PMID 31488864, 2019). "However, administration of JGT to colitis-induced rats significantly decreased levels TNF-α and IL-6, indicating reduced inflammation." (PMID 30800169, 2019).
colitis (continued). "Conversely, during chronic DSS-induced colitis, anti-TNFα antibody treatment of mice reduced intestinal inflammation, implicating a beneficial effect of TNFα signalling during acute colitis but a rather harmful function during chronic colitis induced by DSS." (PMID 30995806, 2019). "Inhibition of TNF-α secretion in IBD correspondingly reduced the severity of colitis." (PMID 31093294, 2019). "Moreover, TNF and TNF-dependent gene expression is upregulated in the colon mucosa from patients affected by colitis as a side effect of ipilimumab and nivolumab." (PMID 31309173, 2019). "However, TNF-α and faecal calprotectin in the pair-fed group were increased as high as or even higher than those in the colitis group." (PMID 31221091, 2019). "TNF-α and IL-6 serum levels were elevated in the colitis group as expected but were reduced by MRS." (PMID 31182999, 2019). "Interestingly, in the more recently described murine model of S. Typhimurium induced colitis after streptomycin treatment, intestinal inflammation was also accompanied by increased levels of TNFα." (PMID 30995806, 2019). "Oral administration of OMVs secreted by EcN has also been described to exert intestinal anti-inflammatory effects in the DSS experimental murine colitis model, reducing the expression of pro-inflammatory cytokines such as IL-1β, TNFα, and IL-17 in comparison with control mice, similarly to live EcN." (PMID 31075872, 2019). "Additionally, distal colons of colitis-induced Flii+/− mice showed significantly lower levels of TNF-α compared to wild-type and FliiTg/Tg counterparts with staining observed in only apical enterocytes." (PMID 31488864, 2019). "Similarly, administration of exogenous H2S significantly reduced TNF-α expression and protein level, which consequently reduced the severity of colitis in rats." (PMID 30704060, 2019). "The significative reduction of the systemic levels of TNFα could be reflecting a neutralization of this cytokine, hitherto a key player of the inflammatory process in human colitis." (PMID 31238939, 2019). "The protective effect of blueberry anthocyanin extract has also been confirmed in trinitrobenzene sulfonic acid (TNBS)-induced colitis mice model, where researchers found that anthocyanin treatment restored not only IL-10 secretion but also reduced serum levels of IL-12, TNF-α, and IFN-γ." (PMID 31137777, 2019). "In fact, plasma TNF-α in CT-1-treated mice with ulcerative colitis is almost normal (i.e., undistinguishable from the controls), whereas it was markedly lower to that found in untreated mice with colitis." (PMID 31805674, 2019). "The results showed that quercetin alleviated the effects of C. rodentium-induced colitis, suppressed the production of pro-inflammatory cytokines, such as interleukin (IL)-17, tumor necrosis factor alpha, and IL-6 (p < 0.05), and promoted the production of IL-10 in the colon tissues (p < 0.05)." (PMID 31156598, 2019). "Astaxanthin induced improvements of various factors in DSS colitis, including: clinical and histological parameters, mRNA expression of inflammatory cytokines (IL-1β, IL-6, TNF-α, IL-36α and IL-36γ), activation of transcription factors NF-κB and AP-1 (c-Jun), and MAPK phosphorylation." (PMID 30705514, 2019). "One might speculate that during the acute DSS-induced colitis model, which mainly focuses on the effects of acute epithelial barrier disruption and innate immune reactions, TNFα might help to reduce intestinal barrier permeability and inflammation." (PMID 30995806, 2019). "Additionally, activation of PXR suppresses the expression of NF-κB target genes including iNOS, IL-1α, IL-1β, IL-6 and TNF-α in the colon of DSS colitis mice." (PMID 31719637, 2019). "Similarly, butyrate was less effective in eliciting an anti-inflammatory response in the TNBS-induced colitis mouse model, vs. an injection of live F. prausnitzii or F. prausnitzii supernatant, while they both induced IL-10 and decreased IL-12 and TNF-α." (PMID 30915065, 2019).